RNU6-67P (RNA, U6 small nuclear 67, pseudogene)
Synonyms: RNU6-67
Gene: Small nuclear RNA gene on chromosome 13 (83,298,071 to 83,298,167, reverse strand). Ensembl gene ENSG00000222791.
Homologues: Orthologues: chimpanzee U6 (100% identical), macaque U6 (86% identical). Paralogues in human: RNU6-19P (89% identical), RNU6-15P (87% identical), RNU6-17P (87% identical), RNU6-18P (87% identical), RNU6-317P (87% identical), RNU6-949P (87% identical), RNU6-1 (86% identical), RNU6-1024P (86% identical), RNU6-1060P (86% identical), RNU6-12P (86% identical), RNU6-13P (86% identical), RNU6-2 (86% identical), and 1287 more.